ENSG00000207147
Synonyms: LOC124900473
Gene: Small nucleolar RNA gene on chromosome 21 (40,513,144 to 40,513,279, forward strand). Ensembl gene ENSG00000207147.
Gene Ontology:
Biological process: RNA processing
Cellular component: nucleolus
Homologues: Paralogues in human: SNORA51 (74% identical).